BRAF (B-Raf proto-oncogene, serine/threonine kinase)
Diseases named in the same sentence as BRAF in open-access papers (continued):
Sharing a sentence is not in itself a finding about the gene and the disease.
melanoma (continued). "EVs from drug-resistant melanoma cells were enriched with the RTK PDGFRβ, and delivering EVs rich in PDGFRβ to metastatic melanoma cells with the BRAF inhibitor-sensitive phenotype activated the PI3K/AKT pathway and resulted in the development of drug resistance." (PMID 34685720, 2021). "The frequency of BRAF mutations in mucosal melanoma is low; hence, most patients with mucosal melanoma do not benefit from BRAF inhibitors alone or in combination with MEK inhibitors." (PMID 34149718, 2021). "Gene expressions in mucosal melanomas like c‐KIT, NRAS or BRAF might be of potential use for selective inhibitors." (PMID 33844113, 2021). "In BRAF mutant melanoma cells, exosomal transfer of proteins to the neighboring cells activates the PI3K/AKT signaling pathway and induces resistance to BRAF kinase inhibitors in patients harboring the BRAF V600E activating alteration." (PMID 33920605, 2021). "Melanoma cells are no exception to the Warburg effect, showing high levels of aerobic glycolysis induced by transformation with oncogenic BRAF or NRAS13." (PMID 33741961, 2021). "Although CDK4/6 inhibition has no substantial effect on the metabolic phenotype following BRAF/MEK targeted therapy in melanoma, CDK4/6 inhibition alone significantly enhances mitochondrial metabolism." (PMID 33572972, 2021). "In a word, compared with gynecologic melanoma, non-gynecologic melanoma harbored distinct mutation rates in KIT, BRAF, SF3B1, KRAS and NRAS genes." (PMID 34102999, 2021). "Earlier we demonstrated that the plasma membrane Ca2+ pump PMCA4b inhibits migration and metastatic activity of BRAF mutant melanoma cells, however, the exact mechanism has not been fully understood." (PMID 33802790, 2021). "PGC1α expression levels have been associated with the metabolic state of melanomas and the response to MEK inhibition independent of BRAF or NRAS mutation status." (PMID 33498757, 2021). "We initially examined TNFα signaling in response to exogenous TNFα in 40 melanoma cell lines, including 31 cutaneous (11 BRAF-mutant, 10 NRAS-mutant, 10 BRAF/RAS WT) and nine uveal melanoma cell lines (five GNAQ-mutant, three GNA11-mutant and one GNAQ/GNA11 WT)." (PMID 34073253, 2021). "Metastatic melanoma (MM) cells (SK-MEL-28 BRAF V600E mutant and SK-MEL-2 BRAF wt) were cultured as a monolayer (2D) or cocultured on 3D dermal equivalents (with fibroblasts) and treated with a BRAFi (vemurafenib) combined with a MEK inhibitor (MEKi, cobimetinib)." (PMID 34638245, 2021). "For OS, a KPS ≥ 80%, a positive BRAF mutation status, a small PTV (planning target volume), the absence of extracranial metastases, as well as a GPA and melanoma molGPA > 2 were prognostic factors." (PMID 33993415, 2021). "Therefore, the BRAF inhibitors vemurafenib and dabrafenib have been approved by the FDA for treatment of melanoma." (PMID 33833342, 2021). "Similar to the results from BRAF+ melanoma patients, serum PLA1A levels were increased in MUT-NRAS melanoma patients compared to the level in the WT-NRAS (36.25 ± 16.24 μg/L vs 29.56 ± 14.26 μg/L), although this difference was not statistically significant (p > 0.05)." (PMID 33723350, 2021). "Similarly, the expression levels of these genes were comparable in BRAF-, NRAS-, and NF1-mutant, as well as triple wild-type melanoma tumors indicating that the presence of mRNAs in qCLASH hybrids is not influenced by stage of disease or mutational background." (PMID 33806450, 2021). "In contrast, YHO-1701 combined with trametinib (MEK inhibitor), vemurafenib, or dabrafenib (BRAF inhibitors) was not preferable, wherein only 4 of 11 drug–cell line pairs were additive or synergistic in the four melanoma cell lines." (PMID 33758275, 2021).
melanoma (continued). "In comparison, normal melanocytes (NHEM) and BRAF wildtype melanoma cell lines (MV3, SK-Mel30) displayed no induction of miR-129-5p expression." (PMID 34063443, 2021). "Also, ALDH1 overexpression in response to BRAF and MEK1/2 inhibition was recently reported in melanoma." (PMID 33803586, 2021). "A recent study demonstrated that uPAR knockdown in combination with vemurafenib administration can inhibit melanoma cell proliferation by decreasing the phosphorylation of AKT and ERK1/2, and overexpression of uPAR results in reduced sensitivity to BRAF inhibition." (PMID 34729105, 2021). "Thus, this screen identified eight out of the 32 small molecule inhibitors that effectively inhibited the survival of both BRAF mutant (M14 and SKMEL-28) melanoma cell lines." (PMID 34771678, 2021). "The oncogenic activities of mGluR1 expressing melanoma cells are independent of BRAF and NRAS mutations; additionally it has been found that a polymorphism in the GRM1 gene is predominately found in non-CSID melanoma patients." (PMID 34359771, 2021). "PLX8394 demonstrated efficacy in inhibiting V600-mutated oncogenic BRAF without activating MAPK simultaneously in colon adenocarcinoma and should be further explored in melanoma." (PMID 33807778, 2021). "Previous study has reported that mutations and deletions of PTEN, negative AKT activation regulator, are more frequent in BRAF mutant rather than NRAS mutant melanomas." (PMID 33734579, 2021). "Of note, icariside II increased mitochondrial ROS levels in resistant melanoma cells with or without vemurafenib, likely preventing BRAF inhibitor resistance via ROS production." (PMID 34830947, 2021). "In line with this, we previously showed that EGFR expression in melanoma models triggers oncogene‐induced senescence in the absence of drugs but becomes beneficial in the presence of BRAF or MEK inhibitors." (PMID 33955157, 2021). "Furthermore, treatments with target specificity for the oncogenic serine/threonine-protein kinase B-Raf (BRAF) proteins, which are universally expressed in melanoma cases, have also shown a significant effect against MM." (PMID 34830431, 2021). "In primary melanoma patient biopsies, NF1 mutations were not correlated with hot-spot BRAF mutations, a finding consistent with a redundant role for these two types of mutations in activating RAS-MAPK signaling." (PMID 34331013, 2021). "In contrast, CD80 and ICOSL are not correlated to the sensitivity of melanoma cells to the BRAF inhibitors." (PMID 34092233, 2021). "BRAF and MEK inhibitors have been developed as a breakthrough treatment for BRAF mutant melanoma patients; however, the development of resistance after a median progression-free survival of just over 12 months in patients with advanced disease remains a clinical challenge." (PMID 33572972, 2021). "As such, numerous MEK inhibitors have been developed for clinical use (e.g. trametinib, cobimetinib, binimetinib) and dual BRAF and MEK inhibition is now considered the standard-of-care over BRAF inhibitor monotherapy for the treatment of BRAFV600 melanoma patients." (PMID 34025662, 2021). "Within the “gene driver free” cohort, in addition to the ETV6→NTRK3 fusion positive LAC, we also detected three rearrangements in three independent melanoma patients: a rare EGFR ex26→LOC100996654 fusion, a BRAF intradomain duplication between ex10 and ex18 and a MET ex14 skipping." (PMID 34282766, 2021). "Because BRAF and NRAS mutations are uncommon in non-cutaneous melanomas, we can consider that each melanoma subtype depends on a different oncogenetic pathway for its development." (PMID 34209084, 2021). "Substantially improved objective response, PFS, and OS irrespective of BRAF status have propelled the nivo + ipi combination as a standard of care in melanoma, despite increases in grade 3–4 adverse events in patients treated with the combination." (PMID 35087529, 2021).
melanoma (continued). "Although acquired activation of PI3K signaling occurs in a subset of resistant melanomas, it remains unclear whether PI3K activation alone is sufficient for the development of BRAF inhibitor resistance." (PMID 34680615, 2021). "Preclinical and translational data demonstrate the immunologic effects of BRAF and MEK inhibitors, including influx of CD4 + and CD8 + T cells into tumors, decreased regulatory T cells (Tregs), decreased MDSCs, and upregulation of melanoma antigens." (PMID 33827575, 2021). "We saw that XAF1 knockdown increased proliferation of NRAS, but not BRAF mutant melanoma cells, yet we acknowledge that this effect was observed in a limited number of cell lines." (PMID 33734579, 2021). "We therefore investigated whether combinations of BRAF-MEK-CDK4/6i and ACT were efficacious in murine models of melanoma." (PMID 34944961, 2021). "For example, in melanoma, the transfer of receptor PDGFRβ by EVs from melanoma donor cells leads to an activation of the PI3K/AKT pathway on BRAF-mutated recipient cells." (PMID 34205256, 2021). "In particular, the BRAF and MEK inhibitors currently in use, such as dabrafenib, vemurafenib and trametinib, showed encouraging response rates but their efficacy is limited by mechanisms of intrinsic or acquired resistance, frequently occurring in melanoma." (PMID 33670365, 2021). "The ability of ID3 to contribute to the resistance to MEKi in both NRAS-mutant (WM4265.2, M93–047) and BRAF-mutant (1205Lu, WM983B) melanomas suggested that it might be a good therapeutic target for melanoma." (PMID 35187538, 2021). "BRAF/MEK inhibitors should be preferred in the adjuvant treatment of BRAF-mutant non-ulcerated melanoma." (PMID 33680957, 2021). "Of the 28 melanoma cell lines, 22 harbored BRAF V600 mutations, 4 harbored oncogenic NRAS mutations, one was NF1‐mutant (in the absence of BRAF or NRAS mutations), and the remainingline was triple‐wild‐type." (PMID 32767816, 2021). "Treatment with BRAF and MEK inhibitors has increased overall survival in melanoma." (PMID 35047063, 2021). "Clinical reports indicate that MGMT promoter is methylated, and thus suppressed, in about 21.5–35% of metastatic melanomas, which entails that inhibition of BRAF, MEK and HDAC could potentially benefit a large number of melanoma patients." (PMID 33800547, 2021). "Unfortunately, the encouraging results with single-agent BRAF inhibitors in melanoma, thyroid cancer, and lung cancer were not confirmed in previously treated BRAF V600E-mutant CRC." (PMID 34572729, 2021). "Combining BRAF with MEK inhibitors shows meaningful clinical efficacy in terms of objective response rates in extracranial melanoma and quite recently, also in intracranial activity with response rates of 44 to 59% in patients with melanoma BM." (PMID 33578810, 2021). "In this study, we found that MitoQ and MitoTEMPO administration had no impact on the number of primary tumors and lymph metastases in mice with BRAF-induced malignant melanoma and no impact on tumor burden in mice with KRAS-induced lung cancer." (PMID 33499262, 2021). "Further research found that combining a MEK inhibitor, binimetinib, with a BRAF inhibitor, encorafenib, as opposed to a BRAF inhibitor alone, yielded long term benefit in progression free survival in patients with melanoma." (PMID 33807778, 2021). "Thus a BRAF independent, FAK-Src-mediated compensatory activation of ERK in melanoma cells directly counteracted the sensitivity to PLX4720." (PMID 34680395, 2021). "Crizotinib was not tested for its efficiency in melanoma but was used as an agent to validate the involvement of HGF release in the resistance to mutant-BRAF inhibitors." (PMID 33918490, 2021).
melanoma (continued). "They revealed a high intensity of immunostaining for BRAF V600E in 60% of the cases in the malignant melanoma group, while not in other skin neoplasms, such as benign nevus." (PMID 33391380, 2021). "This was first observed in human melanoma, where BRAF and NRAS mutations are more frequent but never concur in the same cancer, and is also true for KRAS and BRAF alterations in lung cancer." (PMID 34062774, 2021). "For example, in a BRAFV600E-mutant melanoma model the development of resistance to sequential treatment with the RAFi Vemurafenib, the MEKi Trametinib and the ERKi SCH772984 was shown to be due to progressive increase in BRAF copy number." (PMID 33924486, 2021). "In addition, a significant difference in the increased PLA1A positive cells was found between advanced BRAF/NRAS-MUT melanoma stages and naïve/control melanoma samples." (PMID 33723350, 2021). "In melanoma, both MEK and BRAF inhibition led to an induction of SOX2 that could be reversed by inhibition of DUB." (PMID 33613844, 2021). "A clinical trial called COLUMBUS has shown that the combination of encorafenib and binimetinib therapy for melanoma has the longest median PFS of 14.9 months and a median overall survival of 33.6 months compared to other BRAF-MEK combination therapies with favorable adverse events." (PMID 33622273, 2021). "We also noted a substantial increase in cell surface expression of calreticulin in human SK-MEL-28 melanoma cells, and especially in the IGR39 cell line that is known to be BRAF inhibitor tolerant and displays gene expression signatures linked to immunotherapy resistance." (PMID 33789714, 2021). "Indeed, given that various Receptor Tyrosine Kinases (RTK) can mediate the EMT switch in melanoma, combinations of selected RTK and oncogenic BRAF inhibitors can be successful, such as in the case of the EMT switching inhibitor TGFßR2 with vemurafenib." (PMID 34683910, 2021). "The current standard-of-care for BRAF mutant melanoma is a combination of BRAF and MEK inhibitors, and this combination with the addition of a CDK4/6 inhibitor induces sustained tumour regression in both BRAF and NRAS mutant melanoma preclinical models." (PMID 33572972, 2021). "Furthermore, this research was firstly analyzed with m6A genes in clinical samples that matched clinical pathological features and involved in immune infiltration conceiving the potential therapeutic target on BRAF and MEK in melanoma." (PMID 34446007, 2021). "Based on these, selective inhibition of BRAF has been shown to induce an activated CD8+ T cell infiltrate, as well as increase melanoma MHC expression and melanoma antigen presentation early during treatment both in preclinical models and in human melanoma tissue samples." (PMID 35003090, 2021). "Based on various investigations on the regulatory roleof miRNAs in melanoma, this study was designed to findmiRNAs that can simultaneously target multiple processes,which involved in melanoma progression including EMT,stemness, and BRAF pathway." (PMID 34308569, 2021). "In addition to the PI3K/Akt pathway, BRAF and its downstream MEK/ERK pathway regulates the growth of melanoma cells." (PMID 33478111, 2021).
melanoma (continued). "Exosomes were shown to transfer PDGFRβ to melanoma cells, activating the phosphatidylinositol-3-kinase (PI3K-AKT) signaling pathway, involved in the growth and survival of cancer cells, consequently lowering the sensitivity to BRAF inhibitors." (PMID 34575876, 2021). "In a large series of 706 mucosal melanomas, KIT and BRAF mutational status did not correlate with overall survival (OS); however, NRAS was not analyzed in this series." (PMID 34571863, 2021). "BRAF and MEK combination therapy is a current standard-of-care treatment for BRAFV600 melanoma patients, and the Food and Drug Administration (FDA) has approved three combination therapies; dabrafenib/trametinib, vemurafenib/cobimetinib and encorafenib/binimetinib." (PMID 34830962, 2021). "Combination therapy, however, which includes a BRAF or MEK inhibitor, combined with glembatumumab vedotin (an antibody drug conjugate that targets GPNMB) inhibits GPNMB and effectively controls the growth of Melanoma." (PMID 34570764, 2021). "Amongst the compounds whose IC50 values were in the low micromolar range, Tegaserod (TM), a serotonin receptor 4 (HTR4) agonist, validated successfully in secondary screening approaches with BRAF WT and BRAFV600E human melanoma cell lines and was pursued in further in vitro and in vivo studies." (PMID 32085796, 2020). "Often, patients with resistance develop more metastases and 20% of BRAF mutant melanoma patients never respond to BRAFi due to intrinsic resistance." (PMID 31935375, 2020). "Alterations of the CDK4/6 signaling pathway is observed in different types of melanoma, concomitantly with NRAS, KRAS or BRAF; thus the genetic profiling of CDK4/6 may provide insights for the targeted treatment of various types of melanoma." (PMID 33233603, 2020). "We found that the drugs simultaneously disrupt the BRAF V600E-driven extracellular signal-regulated kinase (ERK) mitogen-activated protein kinase (MAPK) activity and the mechanistic target of rapamycin complex 1 (mTORC1) signaling in melanoma cells." (PMID 32531927, 2020). "Both BRAF/MEK inhibition and ICIs can be used to treat less aggressive BRAF-MT advanced melanoma; however, ICIs may be favored in this population, as they are generally better tolerated." (PMID 32545409, 2020). "The frequency of mutations in the genes is consistent with that reported in the literature for IDH1 and IDH2 in brain tumors, EGFR and KRAS in NSCLCs, KRAS and NRAS in CRCs, BRAF, RAS, PIK3CA, and TERT in thyroid nodules, BRAF, NRAS and cKIT in melanoma, and KRAS in pancreatic pre-operative samples." (PMID 32340363, 2020). "The overall survival at 1, 3 and 5 years after CPI or BRAF-targeted therapy independent of IL-2 immunotherapy in patients with advanced melanoma is significant, yet the reality for the majority of patients is that multiple lines of systemic therapy are needed." (PMID 32467299, 2020). "Moreover, Dinter and collaborators have suggested a potential role of the combination of MEK and BRAF inhibitors, due to the increased levels of endoplasmic reticulum stress detected in NRAS-mutant melanoma cell lines." (PMID 32825562, 2020). "This combination was recently approved by the FDA for the treatment of advanced BRAF-negative melanoma." (PMID 33171792, 2020). "In addition, the melanoma oncogenes BRAF or NRAS, as well as hypoxia, nutrient deprivation, or immune mediators are common stress triggers during melanoma development and maintenance." (PMID 32978520, 2020). "The induction of the noncanonical Wnt pathway by BMI1 was also observed in melanoma cells that were resistant to the treatment of BRAF inhibitor by the upregulation of the Wnt5a and ROR2 receptors." (PMID 32726929, 2020).